FAM241B (family with sequence similarity 241 member B)
Description:
May play a role in lysosome homeostasis.
Synonyms: C10orf35
Tractability: Antibody: UniProt predicts a signal peptide or a membrane-spanning region.
Gene: Protein-coding gene on chromosome 10 (69,630,241 to 69,633,614, forward strand). Ensembl gene ENSG00000171224.
Subcellular location: Membrane
Subcellular location (Human Protein Atlas): Centrosome; Nucleoplasm; Cytosol
Gene Ontology:
Molecular function: protein binding
Cellular component: membrane
Genetic constraint (gnomAD): Loss-of-function variants: 7 observed, 9.85 expected, observed/expected ratio (o/e) 0.71, 90% interval 0.4 to 1.33. That is too few expected variants to judge how well the gene tolerates losing a copy. Missense variants: 136 observed, 165.76 expected, observed/expected ratio (o/e) 0.82, 90% interval 0.71 to 0.95. Synonymous variants: 60 observed, 66.83 expected, observed/expected ratio (o/e) 0.9, 90% interval 0.73 to 1.11.
Homologues: Orthologues: chimpanzee FAM241B (100% identical), macaque FAM241B (98% identical), guinea pig FAM241B (93% identical), dog FAM241B (92% identical), mouse Fam241b (92% identical), rabbit FAM241B (92% identical), rat Fam241b (92% identical), rat Fam241b-ps1 (91% identical). Paralogues in human: FAM241A (24% identical).
Diseases named in the same sentence as FAM241B in open-access papers:
FAM241B is named in the same sentence as 4 diseases in open-access papers, as found by Europe PMC text mining. Sharing a sentence is not in itself a finding about the gene and the disease.
FAM241B shares sentences with these, for which no sentence is quoted: cancer (1 paper); lysosomal disorders (1); Parkinson disease (1); Uterine leiomyoma (1).